IL34 (interleukin 34)
Diseases named in the same sentence as IL34 in open-access papers (continued):
Sharing a sentence is not in itself a finding about the gene and the disease.
cancer (continued). "Additionally, cancer cells may consume IL-34 in certain subtypes at the same time, since CSF-1/CSF-1R but not IL-34 were strongly associated with stromal- and immune-score in HER2 and basal subtypes." (PMID 29796177, 2018). "First, we compared IL-34,CSF-1, CSF-1R, PTPRZ1, and SDC1 gene expression between human MCF7, SK-BR-3 and MDA-MB-231 cancer cells in comparison to human THP-1 macrophages." (PMID 29796177, 2018). "For the cluster on thyroid follicular cell adenomas/carcinomas, no promising effect biomarkers with high specificity were identified, but interleukin-34, oxidative stress, and expression of several genes were found to be related to the adverse outcome." (PMID 41859337, 2026). "The studies on the effects of IL-34 and CCL25 on the TME may provide a better understanding of the clinical significance of CXCL5 in cancer immunotherapy." (PMID 39235457, 2024). "Image registration matching between RNAscope spots and stLearn’s predicted CCI events (IL34 and CSF1R) indeed showed consistent correspondence between the predicted and observed interaction events, mostly at the border between cancer nests and normal tissue areas." (PMID 38007580, 2023). "It has been reported that IL-34 is involved in the M-CSF-mediated pathway to regulate recruitment and/or polarization of TAM, maturing into either M1 and M2 subsets, with M-CSF polarizing TAM into the immunosuppressive, cancer-promoting M2 phenotype." (PMID 35186997, 2022). "IL‐34 expression was detected in cancer cell lines but not in HMDMs, whereas M‐CSF and CCL2 expression was seen in HMDMs but not or rarely in cancer cell lines." (PMID 35132816, 2022). "Since M-CSF-1-R is expressed by additional cell types other than cancer cells, macrophages, and fibroblasts, it is likely that IL-34 can regulate the function of other immune and non-immune cells in the CRC microenvironment." (PMID 34535634, 2021). "Moreover, macrophages stimulated with IL-34 promote differentiation of CCR4 + CCR6 + CD161 + Th17 cells, a phenomenon occurring in many cancers." (PMID 34535634, 2021). "CM of macrophages did not affect IL‐34 expression in cancer cells (data not shown)." (PMID 35132816, 2022). "Indeed, stimulation of DLD-1 cancer cells with IL-34, but not with MSCF1, enhanced the cell proliferation and cell invasion without affecting cell survival." (PMID 29423057, 2018). "However, the mechanism of IL-34 expression in cancer cells has not yet been clarified." (PMID 33072227, 2020). "The expression of IL-34 and the CSFR-1 by both neoplastic and non-tumoral cells within CRC tissue underscores its role in mediating crosstalk between cancer cells and the TME." (PMID 39457693, 2024). "Interleukin-34 (IL-34), a cytokine initially known for its ability to regulate monocyte/macrophage survival and function, is highly produced in human CRC by both cancer cells and non-tumoral cells." (PMID 35837402, 2022). "The expression of IL34 was not predictive of the response to the previous RCC standard-of-care mTOR inhibitor everolimus, which exerts a wide range of anti-neoplastic effects by targeting cancer and stromal cells." (PMID 40538439, 2025). "However, the roles of IL34 and CSF1 at homeostasis or in the context of inflammatory diseases or cancer in wild-type mice have not been clarified in vivo." (PMID 31552020, 2019).
infection (17 papers, 2016 to 2025). The state of being infected such as from the introduction of a foreign agent such as serum, vaccine, antigenic substance or organism. "Recipients were infected with IL-34 overexpression adeno-associated virus, infection efficiency of which was estimated by enzyme linked immunosorbent assay (ELISA), Western blot, and immunofluorescence." (PMID 38230243, 2024). "In a previous report, IL34−/− mice, which have significantly reduced development of microglia, are more susceptible to lethal infection after WNV-NS5-E218A i.c. inoculation." (PMID 30704498, 2019). "There may also be differences between genetic and pharmacological depletion of microglia, as WNV-E218A infection of microglia-deficient Il34–/–mice revealed decreased neuronal and host survival with no change to CNS viral titer, similar to our data." (PMID 37983247, 2023). "The discovery of IL-34 as an alternative CSF1R ligand that is essential for microglial development and the increased sensitivity of IL-34-deficient mice to infection with attenuated WNV highlighted the role of microglia in protection against CNS infection." (PMID 38997413, 2024). "Gene expression analyses showed that IL-18 and IL-34 genes were significantly (p <0.05) upregulated for both cell lines when exposed to mixed species infections." (PMID 37466528, 2023). "Differences between different treatments at the same sampling points on the expression of il-34 and csf-1r resulted in augmented values on fish injected with bacteria especially 48 h after infection." (PMID 35163486, 2022). "Using the Xenopus laevis frog model, we previously established that amphibian MΦs differentiated by IL-34 offer anti-FV3 protection, whereas CSF-1-MΦs render the animals significantly more susceptible to FV3 infections." (PMID 34835105, 2021). "In turn, our present work indicates that while the IL-34-MΦ-mediated anti-FV3 protection is short-lived, the increased frog susceptibility conferred by CSF-1-MΦs extends into chronic FV3 infections, exacerbating the infection outcomes." (PMID 34835105, 2021). "It was upregulated in the spleen after infection with Flavobacterium columnare and grass carp reovirus and in the primary head kidney and spleen leukocytes stimulated with LPS and IL-34." (PMID 33178219, 2020). "After infection, IL-18 and IL-34 geneexpression was measured to assess epithelial cell immune responses, and lactatedehydrogenase (LDH) activity was measured as an indicator of cell damage.Microscopy determined C. albicans morphology and penetration offungal cells through the keratinocyte monolayer." (PMID 37466528, 2023). "The kidneys of IL-34-MΦ-enriched frogs exhibited lower transcript levels of the FV3 immediate early (icp18), delayed early (rad2) and late (mcp) genes than the kidneys of CSF-1-MΦ-enriched frogs at three dpi and the loss of this protection with infection time." (PMID 34835105, 2021). "Presently, we examined the roles of frog CSF-1- and IL-34-MΦs during long-term FV3 infection." (PMID 34835105, 2021). "Perhaps future frog FV3 infection studies in which the proportions of CSF-1- and IL-34-MΦs are altered, may shed additional light upon the dynamics and consequences of the recruitment of distinct leukocyte subsets into virally infected frog tissues." (PMID 34835105, 2021). "Although the proportion of CD8+ CTLs decreased from 5.48% to 4.13% after infection, these cells exhibited enhanced expression of cytolytic genes (nkl, gzmb, gzma, and prf1) and chemokines (ccl5l, ccl20, mcp1b, and ccl4l), while decreased the expression of il34." (PMID 40821846, 2025). "Therefore, it could be hypothesized that both il-34 and csf-1r transcripts seem to play a key role in gilthead seabream survival against Phdp by improving macrophage differentiation at 48 h after infection with Phdp." (PMID 35163486, 2022).
infection (continued). "It will be interesting to explore these notions further in the context of progressing FV3 infections and examine whether this virus manipulates the frog host tissue ratios away from the IL-34-MΦs towards the CSF-1-MΦs within and beyond the timeframe of the FV3 infection studies presented here." (PMID 34835105, 2021). "Moreover, overexpression of IL-34 showed tissue-dependent expression of pro- and anti-inflammatory mediators via JAK/STAT signaling pathways, depending on the manner that was associated with infection resolution." (PMID 33408768, 2021). "Moreover, increased susceptibility to infection has also been shown during the infection with an attenuated strain of WNV in mice lacking IL-34 (absent of microglia but not bone marrow-derived macrophages) therefore confirming the protective role of microglia." (PMID 34916908, 2021). "Interestingly, IL-34 blockade did not alter infection susceptibility, indicating an immunosuppressive effect as observed with CSF-1 blockade can be prevented with anti-IL-34 treatment." (PMID 33162994, 2020). "Presently, we examine the roles played by the frog IL-34- and CSF-1-MΦs during chronic FV3 infections and establish the immunological parameters affected by skewing these frog MΦ populations during infections with this ranavirus pathogen." (PMID 34835105, 2021). "Our past work indicated that during acute infections, the IL-34- and CSF-1-MΦs, respectively, control and facilitate these FV3 infections." (PMID 34835105, 2021). "Given the central role of macrophages and monocytes in infection, we assessed the consequences of neutralizing CSF1 and/or IL34 in mice infected with Listeria monocytogenes." (PMID 31552020, 2019). "The expression of the cytokines IL-18, IL-34 and chemokine CCL28 also increased following infection." (PMID 27677841, 2016). "Moreover, the antiviral effects of IL-34-MΦs are short-lived and are lost as FV3 infections progress." (PMID 34835105, 2021). "As expected, IL-34-MΦ-enriched frogs possessed significantly lower FV3 DNA loads in their kidneys after three days post-infection (dpi), but this protection was lost at later infection times." (PMID 34835105, 2021). "Given the central role of macrophages in fighting infection, long-term blockade of the CSF1R/CSF-1/IL-34 axes could compromise the response to infection." (PMID 32581720, 2020). "The time-course experiment revealed that upon adsorption and early during infection (4 h and 8 h), no significant modulation in the AS profiles of ABI1, CFLAR and IL34 could be detected." (PMID 35489070, 2022).
neurodegenerative disease (12 papers, 2013 to 2025). A disorder of the central nervous system characterized by gradual and progressive loss of neural tissue and neurologic function. "While additional studies are needed to elucidate the potentially divergent roles of M-CSF and IL-34 in HIV-associated neurodegenerative disease, these studies suggest that cFMS signaling through ligation of M-CSF plays an important role in its pathogenesis." (PMID 25886134, 2015). "We extend these findings by showing that in a model of neurodegenerative disease, which is characterized by a pronounced expansion of the microglia population predominantly in the hippocampus, inhibition of IL-34 leads to reduced microglial proliferation." (PMID 33162994, 2020). "IL-34 can substitute M-CSF in osteoclastogenesis however, the current understanding of IL-34 in inflammatory bone-degenerative diseases is limited to a couple of reports concerning RA." (PMID 24339952, 2013). "Twenty-seven of these associations are known disease loci reported in GWAS, including APOE, MME, CD2AP, CD33 and IL34 for AD, and CD40, CD58, EVI5, IL7R and STAT3 for MS, and 23 associations represent previously unreported genetic associations with neurodegenerative diseases." (PMID 40037332, 2025). "In order to provide further proof-of-concept that IL-34 inhibition can be used to tackle neurodegenerative disease, it is inevitable to apply other strategies which offer an improved brain penetrance profile, ideally by using small molecule inhibitors, which to date does not exist." (PMID 33162994, 2020). "We propose that IL-34 inhibition could be a viable strategy to decrease proliferation of microglia in the context of neurodegenerative disease, with restricted impact on peripheral myeloid cells." (PMID 33162994, 2020). "Our results support that modulation of the microglial response via IL-34 blockade could be a potential and more selective therapeutic approach in neurodegenerative diseases." (PMID 32581720, 2020). "In neurodegenerative disease, CSF1R signaling activates proinflammatory processes through the regulation of CSF1 and IL-34 signaling." (PMID 33192177, 2020). "In neurodegenerative disease, CSF1R signaling might activate proinflammatory processes through regulating CSF1 and IL34 signaling." (PMID 32908485, 2020).
brain disease (4 papers, 2019 to 2025). "Overall, our results highlight the challenges of targeting the CSF1R/IL34 axis in the systemic and central compartments, important for framing any therapeutic effort to tackle microglia/macrophage numbers during brain disease." (PMID 33162994, 2020).
kidney disease (4 papers, 2018 to 2024). "Taken together, the intra-renal expression of IL-34 and its receptors could be associated with kidney diseases." (PMID 33428678, 2021). "In kidney diseases, recent reports using mouse experimental models have revealed that not only CSF-1, but also IL-34 was expressed by damaged tubular epithelial cells (TECs) in ischemia/reperfusion (I/R) injury or lupus nephritis (LN)." (PMID 33428678, 2021). "According to recent reviews, the up-regulation of IL-34 is recognized to reflect the activity and/or severity of kidney disease." (PMID 33428678, 2021). "However, in the present study, anti-IL-34 Ab-treated CP-N mice, which exhibited improvements of their renal disorder, showed less infiltration of intra-renal Møs, and decreased expression of inflammatory cytokines and chemokines." (PMID 33428678, 2021). "Thus, IL-34 has potential as a therapeutic target for kidney diseases, and the inhibition of IL-34 with nAb might have a reno-protective effect." (PMID 33428678, 2021). "Prior studies have established the key role of PT-derived IL-34 and macrophage influx in the acute kidney injury and UUO models of kidney disease." (PMID 37906287, 2024). "Hence, the targeting of IL-34 might be a good therapeutic strategy for kidney diseases." (PMID 33428678, 2021).
bacterial infection (3 papers, 2020 to 2021). "In Japanese flounder, IL-34 induced an inflammatory response against bacterial infection characterized by production of pro-inflammatory cytokines, ROS, acid phosphatase activity and inducing cellular resistance." (PMID 33408768, 2021). "Collectively, IL-34 may become an ideal adjuvant to ameliorate the host immune response against viral and bacterial infection in teleost species." (PMID 32231137, 2020). "Therefore, interleukin-34 can be used as a promising adjuvant in DNA vaccines to prevent bacterial infection in fish." (PMID 32231137, 2020). "It has been documented that IL-34 has beneficial effects in viral and bacterial infections." (PMID 32231137, 2020). "In frogs, IL-34 and not CSF1-differentiated macrophages showed an ability to resist bacterial infections." (PMID 33408768, 2021).
Cardiovascular Disease (2 papers, 2023 to 2024). "IL-32 and IL-34 have recently been identified to play a role in specific patient populations with cardiovascular disease." (PMID 36769623, 2023).
colon (2 papers, 2018 to 2020). "Taken together, these findings suggest that, in CRC tissue, IL-34 contributes to maintain the function of type 2-polarized TAMs, with the downstream effect of sustaining colon carcinogenesis." (PMID 33298879, 2020).
infectious disease (2 papers, 2023 to 2025). A disorder directly resulting from the presence and activity of a microbial, viral, or parasitic agent in humans. "IL-34 is suggested asa biomarker for infectious diseases and screening of anti-inflammatory therapies." (PMID 37466528, 2023).
kidney (2 papers, 2022 to 2024). "IL-34 was controversially reported associated with chronic inflammation, acute kidney injury and tolerance in transplantation when expressed by CD45RClo/- T cells." (PMID 38512889, 2024).
retinopathy (2 papers, 2022 to 2024). "Given their heterogeneity, therapeutic agents could be targeted solely to reactive retinal microglial cells, such as IL-34-dependent IPL-resident ones or FGF-2-releasing retinopathy-promoting ones." (PMID 35203414, 2022). "In addition, the downregulation of CD200 and IL-34, which act as immunoregulatory molecules in the serum of HS patients, could negatively influence microglia-mediated retinopathy, as has been recently demonstrated in the diabetic murine model." (PMID 38592296, 2024).
adenocarcinoma (1 paper, 2015). A common cancer characterized by the presence of malignant glandular cells. "However, a higher expression of the IL-34 gene was related to poor survival in a case of adenocarcinoma (GSE31210)." (PMID 25395235, 2015).
inflammation (1 paper, 2015). Aberrant reaction of the microcirculation characterized by movement of fluid and leukocytes from the blood into extravascular tissues. "However, studies of autoimmune rheumatoid arthritis have indicated that IL-34 may be a proinflammatory cytokine with expression associated with joint inflammation." (PMID 26146640, 2015).
neurological diseases (1 paper, 2021). "The role of IL-34 in neurological diseases has gradually attracted attention in recent years." (PMID 34095310, 2021).
respiratory diseases (1 paper, 2025). "Numerous previous studies have established a correlation between IL-34 and various respiratory diseases." (PMID 40176879, 2025).
IL34 also shares sentences with these, for which no sentence is quoted: head and neck cancer (3 papers); ischemic cardiomyopathy (3); Knee Osteoarthritis (3); psoriatic arthritis (3); type 2 diabetes mellitus (3); Crohn disease (2); dyslipidemia (2); Hashimoto thyroiditis (2); ischemic stroke (2); multiple sclerosis (2); non-small cell lung carcinoma (2); prostate carcinoma (2); systemic sclerosis (2); triple-negative breast carcinoma (2); acute graft vs. host disease (1); acute kidney injury (1); acute lung injury (1); acute myocardial infarction (1); amyotrophic lateral sclerosis (1); ankylosing spondylitis (1); arteritis (1); atrial fibrillation (1); autoimmune hepatitis (1); B cell deficiency (1); benign bone tumor (1); bladder cancer (1); blood cancer (1); cholangiocarcinoma (1); chronic inflammatory demyelinating polyneuropathies (1); chronic periodontitis (1).
A further 35 diseases each share a sentence with IL34 in 1 paper.